ADA (adenosine deaminase)
Diseases named in the same sentence as ADA in open-access papers (continued):
Sharing a sentence is not in itself a finding about the gene and the disease.
severe combined immunodeficiency (continued). "The majority of current clinical trials aim at the treatment of adenosine deaminase-deficient severe combined immunodeficiency (ADA-SCID;; X-linked severe immunodeficiency (SCID-X1; or Wiskott-Aldrich syndrome (WAS)." (PMID 37082212, 2023). "The classical example is severe combined immunodeficiency (SCID) with defects in T cells, B cells, and NK cells caused by defects in IL2RG, RAG1/2, ADA, JAK3, and IL7R genes, in which an increased risk of disseminated VZV infection has been well-recognized for many years." (PMID 32495195, 2020). "Fifty-seven paediatric patients (age 0.5–11.4 years) underwent a bone marrow harvest for the purpose of HSPC gene therapy (GT), including adenosine deaminase-severe combined immunodeficiency (ADA-SCID), Wiskott–Aldrich syndrome (WAS) and metachromatic leukodystrophy (MLD) patients." (PMID 31150018, 2019). "In adenosine deaminase-deficient, severe combined immunodeficiency (ADA-SCID) patients and in Wiskott-Aldrich-Syndrome (WAS) patients’ samples, we found evidence for differential circRNA expression of genes that are involved in the molecular pathogenesis of both phenotypes." (PMID 28842720, 2017). "Dysfunction in ADA, the enzyme catalyzing the deamination of adenosine to inosine (see section Contribution of Purinergic Transmission to the Development of the Central Nervous System), is correlated to a severe combined immunodeficiency (named ADA-SCID)." (PMID 29375373, 2017). "Therapeutical success has been obtained in pioneer trials using genetically corrected human bone marrow stem cells to treat patients suffering from X-linked severe combined immunodeficiency (SCID), X-linked adrenoleukodystrophy (ALD) and SCID-adenosine deaminase (ADA-SCID)." (PMID 25724200, 2015). "In 2016, the first ex vivo gene therapy worldwide, StrimvelisTM, based on hematopoietic stem cells (HSC), was approved by the EMA for the treatment of severe combined immunodeficiency caused by adenosine deaminase deficiency (ADA-SCID) in pediatric patients that did not have an adequate cell donor." (PMID 37896191, 2023). "The inherited absence of ADA leads to accumulation of these metabolites that are toxic to rapidly proliferating cells such as lymphocytes, resulting in severe combined immunodeficiency (SCID)." (PMID 30918508, 2019). "Several variations have been identified in the ADA gene, while the structural and functional impact of many of them has not been analyzed yet to emphasize their involvement in severe combined immunodeficiency." (PMID 31781678, 2019). "Accumulation of toxic metabolites of purine nucleotides, normally metabolised by ADA, results in apoptosis in developing lymphocytes, absence of humoral and cellular immune function and severe combined immunodeficiency (SCID)." (PMID 29625577, 2018). "It further proves to be a powerful systemic immunosuppressant as Ado production is used as an immune evasion strategy by pathogens and cancer cells, and its accumulation leads to a severe combined immunodeficiency in patients lacking ADA for Ado degradation." (PMID 29209319, 2017). "For example, in severe combined immunodeficiency (SCID) humans lacking functional T, B, and NK cells due to adenosine deaminase (ADA) deficiency or an IL-2 common receptor gamma chain (IL2γc) mutation (atypical X-linked SCID), opportunistic fungal infections are commonly seen in early life." (PMID 33488563, 2020). "Here, we targeted GSCs aggressiveness with recombinant adenosine deaminase (ADA), which is currently used in other diseases, such as severe combined immunodeficiency (SCID)." (PMID 31671624, 2019).
tuberculosis (138 papers, 2008 to 2026). A chronic, recurrent infection caused by the bacterium Mycobacterium tuberculosis. "Tuberculosis is the leading cause worldwide, and ADA levels >40 U/L strongly suggest tuberculous pleurisy." (PMID 41328078, 2025). "Diagnostic tuberculosis model 2, including the characteristic variables ADA, globulin, and pleural effusion appearance with accuracy, sensitivity, specificity of 95.8, 95.5, and 96.1%, respectively." (PMID 36601381, 2022). "Diagnostic tuberculosis model 1, including characteristic variables ADA, globulin, and tumor cells with accuracy, sensitivity, specificity 97, 94.5, and 99.5%, respectively." (PMID 36601381, 2022). "Increased ADA activity seems to be linked to an activated lymphocyte antigenic response in tuberculosis." (PMID 35894002, 2022). "Further, increased serum/fluid ADA is implicated in several diseases involving stimulation of cell mediated immunity such as tuberculosis, pleurisy, tubercular meningitis, typhoid fever, infectious mononeucleosis and bronchogenic carcinoma, etc." (PMID 33883834, 2020). "ADA levels in pleural effusion have been reported to increase in various causes of pleuritis, including tuberculosis, malignancy (carcinomas, leukemias, and lymphomas), rheumatoid arthritis, and systemic lupus erythematosus." (PMID 32377284, 2020). "Despite the high sensitivity of ADA, its diagnostic specificity is influenced through the local prevalence of tuberculosis, laboratory methodology, population ethnicity and other clinical conditions." (PMID 29308081, 2017). "While Kataria and Imtiaz concluded that ADA testing can be an integral part of diagnostic workup in lymphocyte rich exudative body fluids both in countries with high and low prevalence of tuberculosis." (PMID 21811524, 2010). "While serum adenosine deaminase (ADA) has been associated with tuberculosis-related immune activation, its consistency across different regions and laboratory methods remains unclear." (PMID 42074437, 2026). "ADA is an enzyme synthesized by many cellssuch as mononuclear cells, lymphocytes, neutrophilsand is often associated with intracellular infectionssuch as tuberculosis." (PMID 38084235, 2023). "The lactate dehydrogenase level (5000 IU/L) was found to be high, while the adenosine deaminase level (3 U/L) was found to be below the diagnostic range for tuberculosis (TB)." (PMID 38225554, 2024). "Adding adenosine deaminase (ADA) to the diagnostic tools available to clinicians could help achieve the goal of correctly putting every Rwandan with tuberculosis on treatment, while avoiding unnecessary tuberculosis medications in those who do not have the disease." (PMID 32197582, 2020). "CSF was submitted for bacterial and mycobacterial cultures, and blood cultures were also obtained, along with CSF testing for tuberculosis PCR, adenosine deaminase (ADA) assay, and multiplex PCR." (PMID 40416201, 2025). "Elevated adenosine deaminase (ADA) levels in the fluid (>30 U/L) are highly suggestive of tuberculosis." (PMID 41441583, 2025). "CSF Gram stain, Ziehl Nielsen stain, adenosine deaminase levels, tuberculosis (TB) polymerase chain reaction (PCR), and gene experts for TB were negative." (PMID 40821312, 2025). "This case report highlights the case of an extremely rare case of primary pleural melanoma in a 15-year-old female with left-sided exudative pleural effusion with pleural fluid adenosine deaminase (ADA) in the tuberculosis range." (PMID 40932987, 2025). "In settings where tuberculosis is prevalent, the ADA/CRP ratio serves as a cost-effective and accessible diagnostic tool, augmenting clinicians' ability to diagnose and manage tubercular effusions effectively." (PMID 39205740, 2024). "The relative abundance of T lymphocytes, which orchestrate the inflammatory response to tuberculosis, induces an elevation in ADA levels, particularly noticeable in cases of TBP." (PMID 38178065, 2024).
tuberculosis (continued). "ADA is a T lymphocyte enzyme elevated in diseases like tuberculosis, where cellular immunity is stimulated." (PMID 39715545, 2024). "In cases where lymphocytes predominate in effusions, the most common threshold for an ADA test result indicating tuberculosis (TB) is an ADA level greater than 40 U/L." (PMID 40729167, 2023). "At the moment, it is recommended that recognizing cardiovascular involvement in tuberculosis follow a complex diagnosis, with dosing of ADA and interferon-γ, as well as advanced imaging techniques such as CT and MRI." (PMID 36766543, 2023). "It wasproved that there was a significant difference between serum ADA levels before and after the intensive phaseof tuberculosis treatment (P < 0.001)." (PMID 38084235, 2023). "A tuberculosis smear, culture, and adenosine deaminase test (ADA) were performed to exclude tuberculosis." (PMID 37405045, 2023). "ADA ascitic fluid was significant (66μ/L) and suggestive of tuberculosis, based on ADA ascitic fluid the patient started antituberculous with further deterioration then antituberculous was withdrawn and Ascites were considered to be caused by hypoproteinemia." (PMID 37180328, 2023). "The specificity is 100% for CSF culture and PCR for tuberculosis and that of ADA in CSF is 84%–91%, so these methods are useful for obtaining a definitive diagnosis." (PMID 35371494, 2022). "Ascitic fluid adenosine deaminase (ADA) levels were checked as ADA levels >36I U/L suggest tuberculosis." (PMID 36333730, 2022). "For example, though ADA is one of the best-studied indicators of tuberculosis, increased ADA levels are observed in parapneumonic effusion, empyema, malignant effusion, and rheumatoid arthritis-associated pleural effusion." (PMID 35365722, 2022). "Analysis of the ascitic fluid usually demonstrates a high lymphocyte count, a positive acid-fast bacilli smear, a positive PCR for Mycobacteria tuberculosis and an elevated ADA and LDH level." (PMID 36340021, 2022). "The adenosine deaminase (ADA) value was high (84 IU/L) highly suggestive of tuberculosis, mesothelioma, or lymphoma." (PMID 36531429, 2022). "High levels of adenosine deaminase (ADA) were detected in pleural fluid, consistent with a diagnosis of tuberculosis." (PMID 33748423, 2021). "Previous studies have demonstrated the usefulness of adenosine deaminase (ADA) measurements in the diagnosis of tuberculosis in body fluids, including cerebrospinal, pleural, peritoneal, and pericardial fluids." (PMID 32377284, 2020). "Because the negative predictive value of ADA is as high as 99.9% even in countries with low tuberculosis burden, a low level of ADA activity is frequently considered an exclusion criterion for the diagnosis of TPE in clinical practice." (PMID 31937286, 2020). "One published study suggested that, in a region with a high prevalence of tuberculosis, the routine pleural fluid measurement of ADA concentration among young patients displays a reliable level of diagnostic accuracy." (PMID 32571326, 2020). "ADA levels are increased in rheumatoid arthritis, psoriasis, sarcoidosis, some cancers, and tuberculosis." (PMID 32438744, 2020). "ADA is an indicator of cellular immunity, and its levels are increased in the following diseases: RA, psoriasis, sarcoidosis, cancer and tuberculosis." (PMID 32984382, 2020). "In 7 patients, tuberculosis was diagnosed by elevated ADA alone (3 in pleural fluid, 2 in pericardial fluid, and 2 in ascitic fluid)." (PMID 31041350, 2019). "ADA levels exhibited a significant P value (Dunn's test, P < 0.05) in patients with tuberculosis versus adenocarcinoma, as well as parapneumonic and transudative pleural fluid." (PMID 29854023, 2018). "Diabetic patients are prone to opportunistic infection, thus serum ADA levels in these patients is very important as a screening test for Tuberculosis and autoimmune diseases." (PMID 30126383, 2018).
tuberculosis (continued). "The increased ADA levels in inflammatory and autoimmune diseases such as rheumatoid arthritis, tuberculosis, and systemic lupus erythematosus (SLE) make its role more significant." (PMID 28050278, 2016). "Tuberculosis is cell immune response mediated by T lymphocytes; therefore, the ADA level also increases accordingly." (PMID 27485497, 2016). "An ADA level greater than 35 U/L has a sensitivity of approximately 93 % and a specificity of approximately 90 % for the presence of tuberculosis." (PMID 27287396, 2016). "In this study, CSF findings in scrub typhus meningitis mimicked tuberculosis except for ADA levels (two had ADA ≥10 U/L)." (PMID 27716337, 2016). "Ascitic fluid adenosine deaminase level (ADA) was in the non-tuberculosis range and peritoneal fluid for acid fast bacilli staining and PCR for tuberculosis genome detection were negative." (PMID 26423615, 2015). "When the ADA level in pleural effusion is cut off at 40IU/L, then all of pleural tuberculosis exceeded 40IU/L, while 2.5% of non-tuberculosis disease exceeded 40IU/L." (PMID 26271927, 2015). "ADA levels of two cases of sarcoidosis included in the non-tuberculosis group were less than 40IU/L." (PMID 26271927, 2015). "A tuberculosis smear and culture and adenosine deaminase activity (ADA) should be performed in selected cases when tuberculosis is suspected." (PMID 27335837, 2014). "Meanwhile, the ratio of ADA2 to the total ADA (mean: 90.63%) increased significantly in the tuberculosis group, indicating the increased pleural ADA2 accounts for the high activity of ADA in the effusion fluid." (PMID 24984978, 2014). "As shown in this study, the sensitivity and specificity yielded for ADA on the diagnosis of tuberculosis pleurisy are 76.6% and 83.7%, respectively, which are in agreement with previous studies." (PMID 24984978, 2014). "In the present study, three in house developed diagnostic tests namely TB-Ag(antigen) ELISA, Adenosine deaminase (ADA) estimation and IS6110 polymerase chain reaction (PCR) assay were investigated for the detection of Mycobacterium tuberculosis (M. tb.) infection." (PMID 24069327, 2013). "Tuberculosis was confirmed by pericardial fluid culture in 60% (i.e., definite tuberculous pericarditis) and established by ADA or IFN-γ level in the remainder (i.e., probable tuberculous pericarditis)." (PMID 24155965, 2013). "The newer aids in diagnosing tuberculosis include measuring levels of Adenosine DeAminase (ADA) in the third-space fluids or serum." (PMID 24167730, 2013). "ADA is a T-cell (CD4+) metalloenzyme whose presence in high levels within pleural fluid strongly indicated tuberculosis particularly in high prevalence areas." (PMID 22448326, 2012). "In meta-analyses of 63 studies, ADA is reported to have a sensitivity of 92% and a specificity of 90%, whilst within the setting of a lymphocytic predominant effusion, ADA >40 U/L is almost exclusively secondary to tuberculosis." (PMID 22448326, 2012). "When the histopathological findings of tuberculosis were correlated with pleural fluid ADA levels, among all the histopathologically proved tuberculosis patients, nine patients had ADA level between 40-69 U/L." (PMID 21139714, 2010). "An adenosine deaminase assay, which has been used to identify tuberculosis, was uninterpretable due to the amount of blood in the fluid." (PMID 20684780, 2010). "Out of 20 histological proven tuberculosis cases adenosine de-aminase (ADA) was more than 70 u/l in 11 cases." (PMID 21139714, 2010). "Usefulness of adenosine deaminase (ADA) estimation in pleural fluid has been shown as a reliable chemical biomarker specially when there is suspicion of tuberculosis in endemic areas." (PMID 21811524, 2010). "The second thoracentesis obtained a pleural fluid suggestive for tuberculosis, with a predominance of lymphocytes, an elevated adenosine deaminase level (51 U/l) and a positive tuberculin skin test." (PMID 19175931, 2009).
tuberculosis (continued). "The ADA on the pleural fluid was elevated (51 U/L) and suggestive of tuberculosis, and the TST was positive (20 mm)." (PMID 19175931, 2009). "Adenosine deaminase (ADA) levels are used for diagnosing tuberculosis in several locations and have also been recommended in suspected tuberculous peritonitis." (PMID 18237424, 2008). "If 36 IU/L is taken as cut of limit the sensitiv-ity and specificity of ADA for tuberculosis is 100 % and 77.7 %." (PMID 20165661, 2008). "We found that when more than 100 IU/l was taken as cut of limit of ADA level, it was seen in tuberculosis only." (PMID 20165661, 2008). "The other variables, age, gender, place of residence, history of tuberculosis and high ADA levels, are not statistically associated with treatment failure." (PMID 41427161, 2025). "Additionally, the high adenosine deaminase (ADA) level in the pleural fluid, while suggestive of tuberculosis, underscores the importance of differentiating actinomycosis from other granulomatous infections." (PMID 40027026, 2025). "Diagnostic limitations of pleural fluid analysis often led to reliance on indirect markers such as lymphocytosis or elevated adenosine deaminase (ADA) for suspected tuberculosis, or the presence of atypical/malignant cells for cancer, creating ambiguity in clinical decision-making." (PMID 40978840, 2025). "The ADA level in the pleural fluid argued against the tuberculosis origin of the pleurisy." (PMID 40927193, 2025). "For example, adenosine deaminase (ADA) may be crucial in specific immunity (mutation causes severe combined immunodeficiency) but in different conditions, such as in patients with tuberculosis, when the ADA level in pleural effusion is high." (PMID 39767631, 2024). "In our fourth case, we proceeded with MT despite an elevated ADA level, as the patient lacked significant risk factors for tuberculosis." (PMID 39563685, 2024). "Also, many studies have proved the role of ADA in the response to treatment for tuberculosis at follow up period." (PMID 38084235, 2023). "In addition, histological examination of pleural biopsies identifying caseating granulomas or visualization of acid-fast bacilli in the tissue and/or high levels of adenosine deaminase (ADA) in PF are also relevant guides toward a tuberculosis diagnosis." (PMID 38288122, 2023). "ADA levels indicate tuberculosis by reflecting T-lymphocyte stimulation via mycobacterial antigens." (PMID 40729167, 2023). "Therefore, alow level of ADA does not completely rule out TP, andit is necessary to be very careful in interpreting thelevel of ADA in the mentioned situations, especially ifthere is a clinical suspicion of tuberculosis." (PMID 38084235, 2023). "This study evaluated the ADA and lymphocyte-based criteria for the diagnosis of tuberculous effusion and the different metrics according to age and inflammatory levels in an intermediate tuberculosis burden country, South Korea." (PMID 37864205, 2023). "A total of 10 U/L may be taken as an ideal cut-off value for cerebrospinal fluid adenosine deaminase to diagnose tuberculous meningitis in adults in areas having high prevalence of tuberculosis." (PMID 37404432, 2023). "In regions with a high incidence of tuberculosis, adenosine deaminase (ADA) analysis of pleural effusion may be used to confirm or rule out tuberculous pleuritis." (PMID 38066743, 2023). "ADA could show a relatively low specificity, especially in such inflammatory conditions, confusing the endemic tuberculosis areas." (PMID 35365722, 2022). "ADA is the highest in red blood cells and T lymphocytes, and its activity is directly related to the number and differentiation degree of T cells, while the immunity of tuberculosis is cellular immunity directly mediated by T lymphocytes." (PMID 36157218, 2022).